INS (insulin)
Diseases named in the same sentence as INS in open-access papers (continued):
Sharing a sentence is not in itself a finding about the gene and the disease.
Insulin resistance (continued). "Here, we analyzed whether DEP-1 activity is differentially regulated in liver, skeletal muscle and adipose tissue under high-fat diet (HFD), examined the role of DEP-1 in insulin resistance in vivo, and its function in insulin signaling." (PMID 23889985, 2013). "Here, we assessed whether common single nucleotide polymorphisms (SNPs) in the FNDC5 locus, encoding the irisin precursor, contribute to human prediabetic phenotypes (overweight, glucose intolerance, insulin resistance, impaired insulin release)." (PMID 23637927, 2013). "The surge of epidemiological reports relating insulin resistance and hyperinsulinemia has fueled the idea of the so-called insulin hypothesis of hypertension." (PMID 23573411, 2013). "Given that insulin resistance is a pathological hallmark of MS and T2DM, the activity of GL extracts in improving insulin sensitivity in the skeletal muscles suggest that GL extracts may be valuable for the control of insulin resistance-related MS and T2DM." (PMID 23452929, 2013). "The activity of Jun NH2-terminal kinase (JNK) protein is significantly elevated in various tissues in T2DM patients and animal models, which can impair insulin signaling transduction and lead to insulin resistance through activating the serine phosphorylation of insulin receptor substrate-1 (IRS-1)." (PMID 23829668, 2013). "We genotyped two GCKR variants rs1260326 and rs1260333 in children and adults, and analyzed the association between two variants and triglycerides, glucose, insulin and HOMA-IR using linear regression model, and estimated the effect on insulin resistance using logistic regression model." (PMID 23383164, 2013). "Fasting insulin is a driver of homeostasis model assessment of insulin resistance index HOMA-IR." (PMID 23658795, 2013). "The insulin secretion due to GPR119 activation in insulin resistance was accompanied by significantly increased plasma levels of intact GLP1 already after 5 min (8.6±1.2 vs 3.7±0.9 pg/ml, P=0.004) and levels stayed significantly elevated after 20 min (1.2±0.2 vs 0.6±0.2 pg/ml, P=0.05)." (PMID 23781322, 2013). "Furthermore, this paper is a secondary data analysis of an RCT examining the effects of two diets on the insulin sensitivity of obese adolescents with clinical features of insulin resistance." (PMID 24156290, 2013). "The fact that PPARγ facilitates the maintenance of normal insulin sensitivity leads to the conclusion that its inhibition by TNFα could possibly account for TNFα-induced insulin resistance." (PMID 24324517, 2013). "In addition, it helps to decrease serum levels of glucose, insulin, triglycerides, and uric acid, as well as insulin resistance, and reduces cytokine levels." (PMID 24453416, 2013). "In addition, GSPE treatment (25 mg/kg of GSPE for 21 days) in male rats improves insulin resistance and counteracts the cafeteria-induced effects on insulin synthesis." (PMID 26904613, 2013). "Metabolic and hormonal parameters included glycemia, insulin, insulin resistance, and leptin." (PMID 23587409, 2013). "To understand insulin resistance, we need to clarify molecular mechanisms of insulin signaling." (PMID 23781214, 2013). "The proinflammatory effects of resistin were attributed to its ability to activate NF-kB signaling pathway and subsequently increase the production of proinflammatory cytokines including TNF-α and IL-6, both of which can impair insulin signaling pathways and lead to insulin resistance." (PMID 23772224, 2013). "However, it is increasingly being realized that failure of pancreatic beta cells to secrete enough insulin to adequately compensate for obesity and insulin resistance is the primary defects of T2DM." (PMID 23870481, 2013). "In the present study, impaired insulin secretion and insulin resistance in heterozygous C3H-11NSY mice were similar to those in homozygous C3H-11NSY mice, although not statistically significantly different from those in C3H mice probably due to the small number of mice analyzed." (PMID 23671880, 2013).
Insulin resistance (continued). "In a series of studies in which two different strategies were used to induce mammary tumours in mice in which different genetic manipulations were used to render the mice insulin resistant: it was shown that the insulin resistance consistently increased the number of lung metastases." (PMID 23907184, 2013). "PMA+LES improved insulin resistance as evidenced by decreased serum insulin levels." (PMID 24319483, 2013). "The possible explanation is that SUA increase is individuals with insulin resistance, probably because hyperinsulinemia would cause lower renal UA excretion, and indirect act on SUA via reduction of adipocyte sensitivity to insulin and then increases triglyceride lipolysis within adipose depots." (PMID 23935829, 2013). "Collectively, our data indicate that ER treatment could attenuate serum insulin and leptin levels and increase adiponectin in HF-diet induced obese mice which finally may be benefit to obesity and insulin resistance." (PMID 24312343, 2013). "Type 1 diabetes results from beta-cell destruction, whereas insulin resistance and abdominal insulin secretion are central to the development of type 2 diabetes; therefore, the effects of oxidative stress on insulin resistance are likely to be different based on the type of diabetes." (PMID 24194976, 2013). "Insulin resistance leads to impaired insulin/IGF-1 signaling in skeletal muscle." (PMID 24382946, 2013). "Decreasing SCD1 expression might protect against obesity and insulin resistance, where mice deficient in SCD1 are resistant to metabolic syndrome and are insulin sensitive." (PMID 24381713, 2013). "Adiponectin was significantly and negatively correlated with all measures of insulin resistance, coefficients were r = −0.43 (p = 0.01) with fasting glucose, r = −0.46 (p = 0.004) with fasting insulin, r = −0.34 (p = 0.04) with insulin AUC and r = −0.51 (p = 0.001) with HOMA-IR." (PMID 23870459, 2013). "Previous work focused mainly on the relationship of metabolomic alterations and insulin resistance and results are consistent with effects explained by impaired insulin action, such as diminished plasma amino acids due to increased amino acid oxidation or inadequate suppression of lipolysis." (PMID 24205231, 2013). "The molecular mechanisms whereby GH induces insulin resistance in skeletal muscle, however, remain uncertain, and it is dubious whether they include distinct suppression of insulin signaling." (PMID 23781325, 2013). "We found that PP2A inhibition increased white adipose tissue insulin sensitivity and resulted in a marked enhancement of insulin signaling through the Akt node, but nevertheless exacerbated whole-body and hepatic insulin resistance through an impairment of insulin-stimulated glycogen synthesis." (PMID 24150286, 2013). "The increases in insulin levels might be primarily consequence of the simultaneous presence of insulin resistance in the relevant groups." (PMID 23843789, 2013). "Likewise, insulin resistance promotes brain accumulations of pTau and AβPP-Aβ; AβPP-Aβ toxic fibrils impair insulin signaling by down-regulating insulin receptors." (PMID 25035815, 2013). "A similar result was observed in the absence of significant association of IL-12 with insulin, total cholesterol, and insulin resistance." (PMID 23533314, 2013). "The most consistent findings from these studies were indications of insulin resistance in adulthood based on increased insulin area under the curve (AUC) following an oral or intraperitoneal glucose challenge or on an increased insulin resistance index." (PMID 23232494, 2013). "In this regard, fasting insulin is an imperfect proxy for insulin resistance." (PMID 23806173, 2013). "The term insulin resistance, as generally applied, refers to whole-body reduced glucose uptake in response to physiological insulin levels and its consequent effects on glucose and other insulin-driven metabolic pathways." (PMID 23356701, 2013).
Insulin resistance (continued). "In addition, prolonged high concentrations of circulating insulin, such as those known to occur in insulin resistance, induce increases in renal magnesium excretion, thus perpetuating a deleterious cycle." (PMID 24322525, 2013). "A study on insulin sensitivity in obese adults showed that when the data was adjusted for BMI and visceral adipose tissue, subcutaneous adipose tissue was protective against development of insulin resistance." (PMID 23983688, 2013). "Insulin resistance is characterised by a reduced sensitivity in body tissues to the action of insulin, resulting in impaired glucose uptake in muscle and fat, and diminished insulin suppression of hepatic glucose output." (PMID 24499517, 2013). "Corticosteroids may improve insulin sensitivity in patients with RA, Other studies have shown that a high disease activity is correlated with adverse lipid profile and insulin resistance." (PMID 24205134, 2013). "ER stress potentiates hepatic insulin resistance, and insulin suppresses PDK4 expression." (PMID 23716639, 2013). "Cytotoxic CD8+ T cells are also significantly increased in adipose tissues of obese mice, and depletion of CD8+ T cells reverses inflammation and insulin resistance suggesting that obesity-induced infiltration of CD8+ T cells deteriorate systemic insulin sensitivity." (PMID 23781214, 2013). "In female rats, glucose tolerance also decreased at 25 weeks and thereafter, but insulin was secreted after glucose load, indicating that some factors cause insulin resistance or insulin requirement in the females, unlike in the males." (PMID 23691526, 2013). "As known, T2D develops when insulin secretion is impaired to a level that cannot compensate for systemic insulin resistance, and the presence of obesity can potentiate the progression of both insulin resistance and impaired insulin secretion." (PMID 23700406, 2013). "We found that muscle FGF-21 mRNA was negatively associated with the insulin-mediated glucose-uptake, but not with hepatic insulin resistance (data not shown)." (PMID 23533568, 2013). "Low SHBG and adiponectin levels suggest a post-receptor insulin signalling defect, as observed in other lipodystrophic syndromes, where ectopic fat deposition, particularly in muscle and liver, is thought to play a major role in insulin resistance." (PMID 23849162, 2013). "Treatment with PPARgamma agonists ameliorates insulin sensitivity along with the increase in the plasma adiponectin levels in rodents and human subjects, which at least in part contributes to its ameliorative effect on insulin resistance." (PMID 23935612, 2013). "Thus the definition of insulin resistance is the perturbation of insulin-mediated signaling pathway resulting in systemic hyperglycemia." (PMID 23781214, 2013). "Other mechanisms that have been proposed for the induction of hyperglycemia by SRL include ectopic triglyceride deposition leading to insulin resistance, impairment of insulin-mediated suppression of hepatic glucose production, or a direct toxic effect on pancreatic β cells." (PMID 24151517, 2013). "Insufficient insulin secretion to overcome insulin resistance is also a feature of the condition." (PMID 24236071, 2013). "Insulin resistance was estimated by fasting blood insulin, HOMA-IR and ISI." (PMID 23935881, 2013). "High insulin levels and glucose concentrations above 5.5 mmol/L are associated with enhanced CVD risk and people with prehypertension have been found to have increased insulin resistance." (PMID 23919264, 2013). "Several studies on innate immune cells have demonstrated that the myeloid-derived NLRP3 inflammasome complex may contribute to promote inflammatory cytokine production and insulin resistance through reduction of insulin signaling." (PMID 23843683, 2013). "Next, to test whether protection against high fat diet-induced insulin resistance is mediated by enhanced insulin signaling, we examined insulin-dependent Akt activation." (PMID 23173044, 2012).
Insulin resistance (continued). "Insulin resistance preceded impaired insulin secretion in OLETF rats." (PMID 22257465, 2012). "Remarkably, in a cellular model of “insulin resistance,” where high concentrations of glucose and insulin are exposed to α-cells to mimic hyperglycemia and hyperinsulinemia, subsequent applications of insulin fail to increase GABAAR on the cell surface and fail to inhibit glucagon secretion." (PMID 23316165, 2012). "Circulating levels of plasma triglyceride, an indicator of insulin resistance, showed no significant genetic linkage, suggesting that factors controlling insulin resistance may be distinct from that controlling plasma insulin in our B6XBTBR-ob/ob F2 cross." (PMID 23236292, 2012). "In addition, insulin-responsive tissues, such as muscle, liver, and adipose tissue, exhibit insulin resistance." (PMID 21785581, 2012). "HF-induced insulin resistance is due, in part, to increases in macrophage infiltration and the local levels of TNFα and IL-6 in skeletal muscle and the subsequent deleterious effects of these cytokines on insulin signaling in muscle tissue." (PMID 22272317, 2012). "We further demonstrate that impaired glucose-stimulated insulin secretion and hepatic insulin resistance are mechanisms that may contribute to glucose intolerance in the offspring of PINX mothers." (PMID 22719949, 2012). "Considering that HFD is a known inducer of an inflammatory profile, and given the implication of inflammation in the development of insulin resistance, we developed a diet-induced obesity model to explore the role of the A2bAR in the context of glucose clearance and tissue insulin sensitivity." (PMID 22848385, 2012). "Insulin resistance did not develop until the next day, and was then associated with a boosted insulin response to glucose." (PMID 22747890, 2012). "However, previous observations suggest that alterations in metabolic gene expression are indicative of an impaired hepatic insulin response wherein ID animals exhibited a form of mixed insulin resistance." (PMID 23110872, 2012). "Additionally, saturated fat increases insulin resistance (IR) compared to monounsaturated fat, because it activates serine kinases, thus inhibiting the insulin phosphorylation cascade, decreasing glucose uptake and increasing glycemia." (PMID 22417631, 2012). "In the presence of insulin resistance, excess circulating insulin may prompt an increase in β-amyloid due to their competing demands for IDE." (PMID 22611388, 2012). "However, both Western and Asian type 2 diabetes are characterized by insulin resistance combined with insufficient compensatory insulin secretion to maintain normal glucose control." (PMID 22550941, 2012). "Further, treating patients with hepatitis C genotype 1 and insulin resistance using metformin improves insulin sensitivity and increases SVR rate in patients who reached HOMA lower than 2 at week 24 of therapy and in women, in whom the therapy doubled the SVR rate." (PMID 22412837, 2012). "Furthermore, Mgat2−/− mice exhibited improvement of glucose tolerance and increased insulin sensitivity as assessed by homeostasis model assessment for insulin resistance (HOMA-IR)." (PMID 22698140, 2012). "So, Pauli and colleagues investigated whether this insulin resistance, mediated by S-nitrosation of proteins involved in early steps of the insulin signal transduction pathway, could be reversed by physical exercise." (PMID 23046739, 2012). "The higher level of BMI indicated the stronger of insulin resistance, and patients with strong insulin resistance may need more basal insulin for good glycemic control." (PMID 22720003, 2012). "Obesity-induced ER stress inhibits insulin signaling, and this leads to insulin resistance." (PMID 21785581, 2012). "Individuals with insulin resistance may produce sufficient insulin, but can’t effectively reduce blood sugar level because of resisting the function of the insulin, which mainly involves an impairment of insulin signaling pathway." (PMID 22721429, 2012).
Insulin resistance (continued). "SIRT1 has a potential to act as a ‘thrifty gene’ in Asian populations, mainly Indians, who have fewer cases of obesity but a higher prevalence of T2D at younger ages, probably due to the pronounced dysfunction in early insulin secretion in relation to insulin resistance." (PMID 23133645, 2012). "Impaired insulin resistance and insulin secretion are key determinants of T2DM development." (PMID 22364391, 2012). "Inflammatory mediators may also be increased in T2D and insulin resistance, and inhibit insulin signaling through activation of Jun N-terminal kinase (JNK) and nuclear factor (NF)-κB, thereby causing insulin resistance and interfering with glucose homeostasis." (PMID 23304117, 2012). "Obesity increases insulin production and insulin resistance." (PMID 23213569, 2012). "However, our current study demonstrated nicotine can improve insulin sensitivity in normal rats, which is a state different from obesity induced insulin resistance." (PMID 23251458, 2012). "The authors speculated that the “insulin resistance” in this severe CR group might have the effect of slowing aging, also based on the finding that a number of insulin-resistant strains of mice are long-lived." (PMID 22683661, 2012). "The differences in insulin concentrations and estimated insulin resistance and beta cell function between these population groups were modestly reduced by adjustment for adiposity markers (by approximately 30%); adjustment for adiposity had little impact on differences in other risk markers." (PMID 22558399, 2012). "However, the treatment of T2DM is complicated by several factors inherent to the disease process, such as insulin resistance, hyperinsulinemia, impaired insulin secretion and reduced insulin-mediated glucose uptake and utilization." (PMID 22664465, 2012). "However, chungkookjang had only a small effect on insulin sensitivity, so foods that decrease insulin resistance would be a valuable addition to fermented soybeans." (PMID 23270397, 2012). "Higher C-peptide and insulin levels in CHC patients were already reported supporting the hypothesis that insulin resistance may contribute to fibrotic progression in CHC infection." (PMID 22745767, 2012). "We examined whether anti-TNF therapy improves insulin resistance in RA patients and assessed changes in the insulin signaling cascade." (PMID 22691241, 2012). "The dramatically lower transcript levels of ELOVL6 as well as PNPLA3 in hyperinsulinemic insulin-resistant subjects might have an impact to adipocyte lipid composition and could further decline adipose tissue function in insulin resistance." (PMID 22471940, 2012). "A positive role of myo-inositol in insulin-resistant women with PCOS could depend on defects in the insulin IPG-mediated signaling pathway, that seems to be primarily implicated in the pathogenesis of insulin resistance in this clinical setting." (PMID 22823904, 2012). "In addition, RSV decreases insulin secretion and delays the onset of insulin resistance, possibly by inhibiting ATP- and voltage-dependent channels in pancreatic beta-cells." (PMID 22479589, 2012). "Antihyperglycemic effect of Tecomella undulata in both acute and chronic hyperglycemia may be attributed to increased insulin secretion and improved insulin action (decrease insulin resistance." (PMID 22769229, 2012). "Beta-cells initially increase insulin secretion in response to insulin resistance which may account for the hyperinsulinemia in HFGP males." (PMID 22988521, 2012). "Given the fact that these mice are normoglycemic despite insulin resistance, we speculate that they have higher insulin levels due to compensatory secretion of insulin from pancreas, similar to liver insulin receptor knockout (LIRKO) mice." (PMID 23115649, 2012). "We hypothesize that skeletal muscle SOCS3 contributes to obesity and insulin resistance by antagonizing leptin and insulin signaling." (PMID 23115649, 2012).